TREM2 (triggering receptor expressed on myeloid cells 2)
Diseases named in the same sentence as TREM2 in open-access papers (continued):
Sharing a sentence is not in itself a finding about the gene and the disease.
Stroke (continued). "This is of specific importance as TREM2 is a microglia-specific receptor involved in stroke resolution and microglial function varies between the acute, sub-acute and chronic stroke phase balancing between a pro-inflammatory and pro-regenerative phenotype." (PMID 31379859, 2019). "A third indication of the role of TREM2 in stroke is that TREM2 can inhibit the TLR-mediated pro-inflammatory response." (PMID 31379859, 2019). "Therefore, the diminished number of microglia associated with the stroke lesion in TREM2 KO mice is due to the reduced chemotactic capacity in KO mice, which is supported by a previous study that reports a reduced microglial recruitment to sites of laser-induced neuronal injury in TREM2 KO mice." (PMID 31379859, 2019). "Unfortunately, the role of sTREM2 in ischemic stroke is to date unexplored, and will therefore be left out of consideration for stroke specific microglial TREM2 function in this context." (PMID 31379859, 2019). "Recently, triggering receptor expressed on myeloid cells 2 (TREM2) emerged as a novel microglial target in stroke that is involved in phagocytosis and microglial function." (PMID 31379859, 2019). "Second, TREM2 can drive the pro-inflammatory stroke microenvironment toward a pro-regenerative environment and can therefore exert a neuroprotective effect on the ischemic brain." (PMID 31379859, 2019). "As will be discussed in the next section, TREM2 can interfere in the stroke immune response at multiple levels to determine stroke outcome." (PMID 31379859, 2019). "In vivo, TREM2 KO mice had decreased levels of activated microglia and phagocytes in an experimental stroke model." (PMID 30572908, 2018). "In the CNS, TREM2 expression is increased in the context of traumatic brain injury, stroke, spinal nerve transection, ALS, PD, prion disease, models of demyelination and following beta-amyloid (Aβ) vaccination." (PMID 28768545, 2017). "Recent data provides direct evidence of the beneficial effects of microglial phagocytosis, because transgenic silencing of the phagocytosis receptor TREM2 impairs microglial phagocytosis in vitro and exacerbates ischemic damage in experimental stroke." (PMID 27228556, 2016). "This is in line with recent studies investigating the role of TREM-2 in models of pneumococcal pneumonia, post-stroke inflammation and DSS-induced colitis." (PMID 27253382, 2016). "In contrast, TREM2 KO mice exhibited decreased inflammatory cytokine production compared to TREM2 WT mice in the middle cerebral artery occlusion model of stroke concomitant with decreased localization of activated microglia within the glial scar." (PMID 24893973, 2014). "Significantly fewer Iba1 positive cells were revealed in the glial scar of TREM2-KO mice at day 7 following stroke compared to littermate controls (56% ±6.6, p≤0.001, n = 6 each)." (PMID 23301011, 2013). "To gain more insight into the possible functions of TREM2, we analyzed the post-stroke inflammatory responses in TREM2-KO mice." (PMID 23301011, 2013). "Future work in our laboratory will therefore involve batteries of functional tests on TREM2-KO mice to analyze their motor and learning behavior following stroke." (PMID 23301011, 2013). "TREM2-KO mice and their littermate controls displayed comparable lesion sizes at 7 d and 28 d after stroke (mm3 injured tissue vs. ipsilateral hemisphere in %; 7 d: WT 4.8% ±0.70, KO 5.1% ±0.35, 28 d: WT 3.6% ±0.39, KO 3.0% ±0.27, n = 9–14 each)." (PMID 23301011, 2013). "Although we initially expected an exaggerated pro-inflammatory response following ablation of TREM2, our data support a contradictory scenario that the sub-acute inflammatory reaction after stroke is attenuated in TREM2-KO mice." (PMID 23301011, 2013). "Inflammatory mediator transcription was unaltered between TREM2-KO mice and littermate controls at 12 h after stroke, indicating a similar acute inflammatory response." (PMID 23301011, 2013).
Stroke (continued). "This attenuated microglial activation was accompanied by a lower occurrence of CD3-positive T-cells in the infarct core of TREM2-KO mice 28 days after stroke." (PMID 23301011, 2013). "We found an unchanged TREM2 expression at early reperfusion times (hours), but a strong TREM2 up-regulation 7 and 28 days after stroke (up to 10 fold)." (PMID 23301011, 2013). "Next, we analyzed cytokine gene transcription after stroke by comparing TREM2-KO mice with littermate controls." (PMID 23301011, 2013). "At 7 d after stroke, littermate controls and TREM2-KO mice exhibited a similar number of CD3-positive T-cells (100% ±5.72 and 102% ±7.71, respectively)." (PMID 23301011, 2013). "TREM2 regulates microglial lipid metabolism, reducing stroke inflammation." (PMID 40880849, 2025). "Promoting the expression of TREM2 may become one of the important directions for reducing stroke brain damage and improving prognosis in the future." (PMID 40864831, 2025). "Furthermore, the infiltration of CD3+ T cells is decreased at 28 days after stroke in TREM2-KO mice." (PMID 40242752, 2025). "In clinical studies, TREM2 is cleaved to myeloid soluble trigger receptor 2 (sTREM2) in plasma extracted from patients with ischemic stroke within 24 h, results of which suggest that early increase in sTREM2 levels is a predictor of poor outcome in stroke." (PMID 40864831, 2025). "In addition, NEAT1 downregulation significantly upregulated the expression of TREM2 in stroke animals." (PMID 38212456, 2024). "Augmenting TREM2 signaling in monocytes/macrophages represents a promising therapeutic approach to enhance efferocytosis and promote inflammation resolution following stroke." (PMID 39660125, 2024). "These stroke-associated white matter microglia (SAWM) showed lower expressions of the homeostatic microglial markers (P2ry12, Tmem119, etc.)along with elevated expressions of the DAM- and/or MGnD-related genes (Apoe, Trem2, Ctsb, Ctsd, etc.)." (PMID 38509618, 2024). "However, the mechanism and temporal dynamics of TREM2 in regulating phenotypes after stroke are currently unclear and require further investigation." (PMID 37361996, 2023). "Although upregulation of TREM2 expression by PE plays an important role in white matter repair after stroke, optimal TREM2 level and duration of its upregulation, as well as its role in inhibiting neuronal apoptosis should be elucidated through further studies." (PMID 36829205, 2023). "In addition, after experimental stroke, the TH1-mediated effects on the microglial transcriptomic profile were associated with an increase of Trem2 expression, a key marker of DAM in various brain disorders, in comparison to microglia primed by TREG cells." (PMID 36512388, 2022). "Previous experimental evidence based on middle cerebral artery occlusion mice indicated that TREM2 has crucial effects on stroke immune response, suggesting TREM2 could be a promising immunomodulation target in ischemic stroke." (PMID 35414082, 2022). "TREM2 participates in phagocytic activity following experimental stroke." (PMID 35082781, 2021). "Decreased TREM2 expression was correlated with robust post-stroke neural inflammation and exacerbated stroke outcomes, which indicated that inhibition of TREM2 signaling in macrophages was the potential mechanism involved in the detrimental impact of the high-salt microenvironment." (PMID 33845849, 2021). "Enhancing TREM2 signaling in monocytes/macrophages could be a promising therapeutic strategy to enhance efferocytosis and promote post-stroke inflammation resolution." (PMID 33845849, 2021). "TREM2 has also been shown to be important for angiogenesis following stroke." (PMID 28768545, 2017). "Interestingly, it was a contradictory scenario that attenuated inflammatory response in TREM2 knockout mice following stroke." (PMID 28592261, 2017). "Similarly, genetic deletion of TREM-2 leads to a decreased production of TNF-α, IL-1β and IL-6 after stroke, associated with reduced microglia activation." (PMID 25347935, 2014).
Stroke (continued). "Thus, a reduced gene transcription of pro-inflammatory cytokines was detected in TREM2-KO mice selectively at 7 d after stroke, a time point that also showed the highest TREM2 expression levels in diseased littermate control mice." (PMID 23301011, 2013). "Indeed, TNFα, IL-1α, IL-1β, CCL2, CCL3 and CX3CR1 transcript expression differed in the ischemic cerebral tissue of TREM2-KO mice compared to littermate controls at day 7 after stroke." (PMID 23301011, 2013). "The present study focuses on the role of TREM2 in inflammatory processes after stroke." (PMID 23301011, 2013). "Whereas all investigated chemokines were found to be unchanged in their acute response at 12 h after stroke (TREM2-KO vs. WT), the increased expression of CCL3 and CCL2 was attenuated in TREM2-KO mice at 7 d after stroke (CCL3: to 12% ±1.3, CCL2: to 37% ±6.5, p≤0.05, n = 5/6 each)." (PMID 23301011, 2013). "A further question that arises is whether these altered inflammatory processes in TREM2-KO mice have beneficial or deleterious functional consequences following stroke." (PMID 23301011, 2013). "Quantitative PCR (qPCR) revealed a greatly increased transcription of TREM2 after stroke." (PMID 23301011, 2013). "Thus, reduced microglial activation and reduced expression of chemokines at day 7 after stroke were followed by a diminished invasion of CD3-positive T-cells in TREM2-KO mice." (PMID 23301011, 2013). "Moreover, the amount of CD3-positive T-cells in TREM2-KO mice 28 d after stroke was at a comparable level as observed 7 d after stroke in littermate controls and TREM2-KO mice." (PMID 23301011, 2013). "However, in the sub-acute phase (7 d reperfusion) following stroke, TREM2-KO mice showed a decreased transcription of pro-inflammatory cytokines TNFα, IL-1α and IL-1β, associated with a reduced microglial activity (CD68, Iba1)." (PMID 23301011, 2013). "We therefore conclude that TREM2 appears to sustain a distinct inflammatory response after stroke." (PMID 23301011, 2013). "Moreover, TREM2 facilitates efferocytosis of dying cells following experimental stroke." (PMID 39660125, 2024). "However, the effect of PE on TREM2 expression after stroke remains unreported." (PMID 36829205, 2023). "Therefore, it is necessary to investigate whether PE modulates micrlglial state and promotes remyelination after stroke via TREM2." (PMID 36829205, 2023). "In addition, physical exercise promoted TREM2 expression in MCAO rats up to 35 days after stroke." (PMID 36829205, 2023). "Consistent with this hypothesis, TREM2 knockdown in BV2 microglia attenuated phagocytosis of oxygen-glucose-deprived neurons in vitro, and likewise TREM2 deficiency in vivo reduced phagocytosis of ischemic brain parenchyma in an experimental stroke model." (PMID 26337043, 2015). "In addition to central nervous system diseases, TREM2 also participates in inflammatory diseases, such as cirrhosis, inflammatory bowel disease, chronic obstructive pulmonary disease, multiple sclerosis, stroke, cholestasis, sepsis, acne, and leprosy granulomas." (PMID 38236825, 2024). "Accumulating evidence underscores the significant impact of the Triggering receptor expressed on myeloid cells-2 (TREM2)-activating protein of 12kDa (DAP12) system in central nervous system CNS disorders such as neurodegenerative diseases and stroke." (PMID 39660125, 2024). "Though the main cytokines and chemokines revealed an attenuated expression in the sub-acute phase following stroke, chemokine receptors CCR1, CCR2 and CCR5 were found to be unaltered following TREM2 knockout." (PMID 23301011, 2013). "Thus, TREM2 might play a critical role within the subacute phase after stroke." (PMID 23301011, 2013). "Relevant to this point, in a database analysis of carotid endarterectomy samples from recent stroke patients and non-stroke controls, TREM2 was enriched in the non-stroke patients, suggesting that TREM2 promoted a stable plaque phenotype." (PMID 39742252, 2024).
Stroke (continued). "It should be noted that to date, no stroke stage-specific reports are available that go into detail in TREM2 expression dynamics and pathways that lead to TREM2 upregulation and effector mechanisms." (PMID 31379859, 2019). "No increased gene transcripts for TREM2 were observed after stroke in littermate controls (WT) at the contralateral side and in sham-operated mice." (PMID 23301011, 2013). "Stroke was induced in C57BL/6 mice by MCAO and gene transcription of TREM2 was monitored." (PMID 23301011, 2013). "Next, we investigated whether the attenuated release of chemokines by activated microglial cells in TREM2-KO mice impacts the invasion of leukocytes by determining the number of invasive CD3-positive T-cells immunohistochemically at 7 d and 28 d after stroke." (PMID 23301011, 2013). "However, 28 d after stroke, the number of CD3-positive T-cells was reduced in TREM2-KO mice (90% ±8.4) compared to littermate controls (132% ±9.3, *p≤0.05, n = 3 each)." (PMID 23301011, 2013). "However, the TREM2 pathway was not altered in ICAM and IPAM, suggesting a difference in the formation of these two stroke-associated microglial subclusters and DAM." (PMID 38082331, 2023). "Interestingly, microglial TREM2 expression, and not TREM2 expression on circulating macrophages, was fundamental in stroke outcome." (PMID 35177618, 2022). "In addition, mice with no intact microglial TREM2 demonstrated a lower number of phagocytes near the stroke lesion that also showed reduced phagocytic activity." (PMID 31379859, 2019). "At 28 d following stroke, a strong invasion of CD3-positive T-cells was observed in the infarct core of littermate control mice, whereas such a change was absent in TREM2-KO mice." (PMID 23301011, 2013). "Through Spearman correlation analysis, we determined that the CD206 MFI of peripheral blood monocytes showed a significant positive correlation with TREM2 MFI in stroke patients, while the CD80 MFI showed a negative correlation with the TREM2 MFI, which was consistent with our data in animal models." (PMID 33845849, 2021).
atherosclerosis (46 papers, 2020 to 2025). A disease characterized by the build-up of fatty material and calcium deposition in the arterial wall resulting in partial or complete occlusion of the arterial lumen. "TREM2 deficiency in hematopoietic cells increased the necrotic core size in early atherosclerosis, demonstrating the contribution of TREM2 in foamy macrophages to the clearance of dead cells (efferocytosis)." (PMID 40305368, 2025). "Studies have shown that hematopoietic or global TREM2 deficiency increased, whereas TREM2 agonism decreased, necrotic core formation in early atherosclerosis." (PMID 41000074, 2025). "Myeloid LXR deficiency was shown to dramatically increase atherosclerosis, with increased numbers of TREM2 foamy macrophages." (PMID 39742252, 2024). "In mouse atherosclerosis studies in which TREM2 was deficient in monocytes/macrophages, hematopoietic cells or globally, there was no consistent change in necrotic core size, however." (PMID 39742252, 2024). "Here we show that hematopoietic or global TREM2 deficiency increased, whereas TREM2 agonism decreased, necrotic core formation in early atherosclerosis." (PMID 38974464, 2024). "Strikingly, LTBP was readily detectable in control samples but clearly diminished in Trem2-deficient mouse AG after atherosclerosis." (PMID 38869957, 2024). "We thus assessed the expression of the phagocytic receptors MERTK and TREM2, which have both been implicated in efferocytosis and necrotic core formation in atherosclerosis." (PMID 39531316, 2024). "This analysis suggests that TREM2 affects expression of genes associated with the foamy macrophage signature, lipid uptake and pro-survival activities in atherosclerosis-associated foamy macrophages." (PMID 38974464, 2024). "Based on this, we conclude that Trem2 deficiency drives two downstream outcomes that contribute to atherosclerosis protection." (PMID 38646596, 2023). "Trem2 is implicated in lipid influx and foam cell formation in atherosclerosis, and Trem2+ LAM upon lipid uptake become foam cells." (PMID 37781401, 2023). "We also identified a separate population of LYVE1+ macrophages (My.6) also expressing high levels of TREM2, a gene previously implicated in antiinflammatory macrophages in murine atherosclerosis." (PMID 37471165, 2023). "The identification of arterial leukocytes in a murine atherosclerotic aorta model revealed a subset that is associated with atherosclerosis and expresses Trem2." (PMID 36982629, 2023). "The loss of myeloid LXR reduces the expression of Trem2 and its related genes, thus promoting atherosclerosis progression." (PMID 36994095, 2023). "The precise effects of Trem2 deficiency on macrophage function in atherosclerosis in mouse models may be complex." (PMID 40152781, 2025). "Excessive inflammatory response is closely associated with the deterioration of atherosclerosis, so the role of TREM2 in this process may be very important." (PMID 39497214, 2024). "Additionally, we discuss potential diagnostic and therapeutic approaches for atherosclerosis that target TREM2." (PMID 39497214, 2024). "Furthermore, the TREM2 variant rs6918289 has been associated with increased risk of atherosclerosis." (PMID 36966244, 2023). "In Trem2-deficient foamy macrophages, the cholesterol biosynthesis pathway cannot be downregulated, leading to impaired lipid uptake, increased mortality of foamy macrophages, inhibited clearance of apoptotic cells, and ultimately, the development of atherosclerosis." (PMID 41000074, 2025).